APC (APC regulator of Wnt signaling pathway)
Diseases named in the same sentence as APC in open-access papers (continued):
Sharing a sentence is not in itself a finding about the gene and the disease.
polyp (23 papers, 2006 to 2025). A usually exophytic mass attached to the underlying tissue by a broad base or a thin stalk. "FAP patients with mutations in other APC gene regions tend to exhibit an intermediate phenotype, characterized by polyp numbers between the hundreds and thousands." (PMID 40695959, 2025). "The system usually starts with a mutation in the adenomatous polyposis coli (APC) gene, a tumor that causes benign adenoma or polyp formation." (PMID 37427139, 2023). "For instance, Adenomatous polyposis coli (APC) mutation-associated polyps are usually found in the colorectum in human, while APC-induced polyp formation occurs preferably in the small intestine in mice." (PMID 34599392, 2021). "Patients harboring the FAP1 and FAP2 APC mutations presented a more severe clinical manifestations of the disease, with higher polyp burden and had undergone colon removal surgery due to increased risk for developing CRC." (PMID 33664379, 2021). "Mutations in the APC gene are highly associated with polyp development and regarded as an early step in neoplastic transformation, and we found mutations in this gene at a high frequency in both CAP and CFPs1." (PMID 29453410, 2018). "Duodenal polyp burden is milder on average in individuals with APC mutations associated with AFAP versus FAP, but severe duodenal polyposis is observed in AFAP." (PMID 30012100, 2018). "Mutations in adenomatous polyposis coli (APC) gene can lead to the activation of the wingless-type (Wnt) pathway, a common mechanism for initiating polyp to cancer progression sequence." (PMID 26840292, 2016). "In this case, it is apparent that biallelic MYH mutations have played a role in the early stages of colorectal carcinogenesis through APC mutation and polyp formation." (PMID 17031395, 2006). "However, truncated APC mutations prevent effective degradation of β-catenin, so accumulated nuclear β-catenin induces expression of the target genes associated with polyp formation and initiates colorectal carcinogenesis." (PMID 37760541, 2023). "We initially hypothesized that polyp emergence in the FAP patient corpus was due to somatic mutation resulting in APC loss of heterozygosity." (PMID 37943618, 2023). "Deletion of IL-17, IL-6, CCR2, or TNF-receptor p55 led to a suppression of intestinal polyp development or CAC development in both the APC-mutant and the AOM/DSS models." (PMID 26543325, 2015). "Hence, both macrophages and mast cells are required to elaborate the microenvironment in which mutant APC can induce polyp formation." (PMID 26543325, 2015). "In mutant APC intestinal polyposis models, CSF-1-dependent TAMs promote polyp growth." (PMID 23372702, 2013). "While animals did not develop invasive cancer, and instead died due to polyp load, these data indicate that the commutation of APC and BRAF in an enterocyte induces rapid neoplastic alterations and an overt proliferative phenotype." (PMID 32384699, 2020). "Notably, we did not detect significant nuclear enrichment of β-catenin in N14-77 polyp cells, which does not support APC inactivation." (PMID 30018743, 2018).
gastric adenocarcinoma (22 papers, 2010 to 2026). "Variants in the APC promotor 1B region cause the relatively newly described condition of gastric adenocarcinoma and proximal polyposis of the stomach (GAPPS)." (PMID 40237877, 2025). "According to the cBioPortal website, KRAS and APC variants occur in 15% and 12% of stomach adenocarcinoma, respectively." (PMID 40916582, 2025). "Particularly, APC mutations alter cell cycle regulation and protein expression in the diffuse type of gastric adenocarcinoma." (PMID 34068652, 2021). "To clarify the role of APC gene mutations in the development of diffuse type gastric adenocarcinoma, we have investigated the mutations in the exons 14 and 15 of APC gene in a North East Indian population." (PMID 28576136, 2017). "Our study showed that mutations in the APC gene alter the protein expression and cell cycle regulation in diffuse type gastric adenocarcinoma." (PMID 28576136, 2017). "Finally, mutation of the APC promoter 1B, which is a characteristic of gastric adenocarcinoma and proximal polyposis of the stomach (potentially resembling IEFN), was detected in only one IEFN case." (PMID 32533343, 2020). "Our study showed that mutations in APC can contribute to development of diffuse type gastric adenocarcinomas by altering the APC protein expression and cell cycle regulation and additional genetic changes could account for the differences in pathology." (PMID 28576136, 2017). "Interestingly, multiple adenomas in the stomach, in addition to the commonly detected fundic gland polyps, as well as in the duodenum were observed in 2 of our 3 AFAP patients with germline mutations in APC exon 4, and a gastric adenocarcinoma was also found in one of them at 34 years of age." (PMID 21078199, 2010). "The three primary familial gastric cancers include hereditary diffuse gastric cancer, familial intestinal gastric cancer and gastric adenocarcinoma and proximal polyposis of the stomach, caused by germline mutations in genes such as CDH1, CTNNA1 and APC." (PMID 34359744, 2021). "Of note, allelic imbalance of APC can be detected in the blood and saliva of patients with gastric adenocarcinoma and proximal polyposis of the stomach (GAPPS), which place APC as an excellent prognostic marker." (PMID 29570681, 2018). "Gastric adenocarcinoma and proximal polyposis of the stomach (GAPPS) is a rare disease and characterized by a unique point mutation in the promoter 1B region of the adenomatous polyposis coli (APC) gene." (PMID 35435526, 2022). "APC expression gene was decreased in gastric adenocarcinoma." (PMID 32764696, 2020). "Gastric adenocarcinomas have been reported in (A)FAP patients, but the mechanism of involvement of the APC mutation in the gastric carcinogenesis remains largely unknown." (PMID 21078199, 2010). "The recent Cancer Genome Atlas paper, which analysed 295 primary gastric adenocarcinomas, identified that APC is the 6th most frequently mutated gene in the non-hypermutated gastric tumours (over three times more frequent than the hypermutated subgroup which does not contain APC mutations)." (PMID 27196929, 2016).
metastatic tumors (21 papers, 2013 to 2026). "The APC mutation rate was significantly higher in pT4 than in pT1-3 but tended to be lower in metastatic tumors." (PMID 35778698, 2022). "Single-cell data also revealed a striking independent tumor lineage that did not metastasize, and early progenitor clones with the “first hit” mutation in APC that subsequently gave rise to both the primary and metastatic tumors." (PMID 34833475, 2021). "This case also had mutations for APC, KRAS and SMAD4 which were identical in the primary and metastatic tumours." (PMID 37670299, 2023). "Our OS analysis suggests that APC/CTNNB1 somatic mutations may have some role in regional metastatic and, even more so, in distant metastatic disease." (PMID 34986841, 2022). "The frequency of mutations was numerically higher in primary tumors than in metastatic tumors in APC, although, there was no overall statistical difference in the frequency of mutations between primary and metastatic tumors." (PMID 34074070, 2021).
non-small cell lung carcinoma (21 papers, 2010 to 2025). A group of at least three distinct histological types of lung cancer, including non-small cell squamous cell carcinoma, adenocarcinoma, and large cell carcinoma. "APC loss through mutation or promoter hypermethylation occurs in many different cancer types, including colon, prostate, breast, and non-small cell lung cancers." (PMID 33105836, 2020). "Loss of heterozygosity of APC has been shown in both small cell and non-small cell lung cancers, but appears to be more frequent in SCLC." (PMID 20624269, 2010). "However, the diagnostic role of APC promoter methylation in non-small cell lung cancer (NSCLC) remains unclear." (PMID 24661338, 2014). "For example, the hypermethylation of four genes, CDKN2A, cadherin 13 (CDH13), RASSF1, and APC, can be used to predict tumor progression of stage 1 non-small cell lung cancer (NSCLC)." (PMID 27895806, 2016).
dysplasia (19 papers, 2008 to 2025). A usually neoplastic transformation of the cell, associated with altered architectural tissue patterns. "Sporadic FGPs without dysplasia have mutations in the gene encoding β-ceratin (CTNNB1) but lack APC alterations, whereas sporadic FGPs with low-grade dysplasia display APC alterations but usually lack germline mutations in the CTNNB1 gene." (PMID 36553595, 2022). "Adenomatous polyposis coli (APC) mutations are rare events in the UC-associated dysplasia–carcinoma sequence (27.5% of HGD cases) compared with 50% in the typical adenoma–carcinoma sequence." (PMID 28621756, 2017). "Eads and colleagues have previously shown APC promoter hypermethylation in Barrett's epithelium, either in metaplasia, dysplasia and adenocarcinoma of esophagus." (PMID 19149902, 2009). "Across dysplasia samples, multiple oncogenic drivers were seen, including APC, KRAS, and SMAD4 mutations, with no alterations clearly emerging in the transition to carcinoma." (PMID 36611031, 2023). "There was no remarkable difference in the distribution of promoter methylation in the APC gene (mean 9%): for in situ carcinoma, the mean promoter methylation in affected tissue was 8% and in adenomas it was 8.4% (9.1% for low grade and 6.8% for high grade dysplasia)." (PMID 35173208, 2022). "However, localization of APC in dysplasia samples was mostly membranous." (PMID 34564680, 2021).
familial colorectal cancer (19 papers, 2001 to 2025). Familial colon cancer is a cluster of colon cancer within a family. "Adenomatous polyposis coli (APC) is a multifunctional tumor suppressor gene mutated in approximately 80% of sporadic and hereditary colorectal cancer (CRC) syndrome tumors." (PMID 37943958, 2023). "Furthermore, the development and progression of hereditary colorectal cancer, often caused by mutations in tumor suppressor genes such as adenomatous polyposis coli (APC), have also been found to be influenced by the microbiota." (PMID 39969175, 2025). "Indeed, nonsense mutations in adenomatous polyposis coli (APC), which suppresses Wnt signaling as a tumor suppressor, increase the risk of sporadic and hereditary colorectal cancer." (PMID 35453543, 2022). "Among the 220 patients without hereditary colorectal cancer, those with early recurrence more often had APC mutations than those with late recurrence (29.7% vs. 17.4%, p = 0.037)." (PMID 33919924, 2021). "In general, APC mutations appear to be associated with early tumor recurrence in patients without hereditary colorectal cancer." (PMID 33919924, 2021). "In the present study, among 236 CRC patients with tumor recurrence, the frequency of APC mutations was 37.5% and 24.5% in those with and without hereditary colorectal cancer, respectively (p = 0.251)." (PMID 33919924, 2021).
intestinal polyp (19 papers, 2009 to 2025). Discrete abnormal tissue masses that protrude into the lumen of the intestine. "Comparable murine APC alleles also evoke intestinal polyps, which are typically confined to the small intestine and proximal colon, but do not progress to carcinoma in the absence of additional mutations." (PMID 33525395, 2021). "Some of these substances showed promising results in vitro and in vivo such as SK-116, which reduced serum PAI-1 levels and the number of intestinal polyps in mice with APC mutations." (PMID 33097058, 2020). "We also examined whether the vaccine would inhibit the development of intestinal polyps in APC Min mice, which have a mutation in the APC gene." (PMID 34526999, 2021). "Over 1400 different mutations of this gene have been reported, and the specific area of the APC gene affected determines the extracolonic presentation as well as the number, time frame, and the malignant potential of the intestinal polyp." (PMID 38576527, 2024). "Together, these findings suggest mTOR and elevated Myc as a vulnerability in mutant APC-driven intestinal polyps, and a potential role of cell death in the activation of local immune environment." (PMID 37138032, 2023). "It has been observed that inhibiting the mTORC1 pathway in APC mutant mice by administering the drug RAD001 (Everolimus) results in the reduction of intestinal polyps and death rate in animals." (PMID 37280524, 2023). "The number of intestinal polyps in APC-WT and APC-KRASG12D mice was counted at different time points." (PMID 32228650, 2020). "Increased levels of SIRT1 control fibroblast activation and tissue fibrosis, while, SIRT1 inactivation, reduces the growth and number of intestinal polyps in the APC+/min mice model." (PMID 32655835, 2020). "Dysregulated Wnt/β-catenin signaling has been shown to induce mTOR expression and signaling in intestinal polyps of mutant APC mice, and we have shown that mTOR expression is elevated in uteri of Amhr2-Cre;Ctnnb1Δ(ex3)/+ mice." (PMID 21695255, 2011). "Notably, these low-Wnt or P-N organoids were derived from a variety of patients with FAP without obvious associations with APC genotype or clinical features such as proton pump inhibitor usage, gastric polyp phenotype, or intestinal polyp burden." (PMID 37943618, 2023). "In this hereditary cancer syndrome, loss of APC function leads to the inappropriate stabilization of β-catenin and the formation of constitutive complexes with the TCF family, leading to the expression of downstream genes that result in the development of intestinal polyps." (PMID 28406434, 2017).